TRAJ7 (T cell receptor alpha joining 7)
Gene: T-cell receptor joining (J) gene on chromosome 14 (22,537,622 to 22,537,680, forward strand). Ensembl gene ENSG00000211882.
Diseases named in the same sentence as TRAJ7 in open-access papers:
TRAJ7 is named in the same sentence as 1 disease in open-access papers, as found by Europe PMC text mining. Sharing a sentence is not in itself a finding about the gene and the disease.
TRAJ7 shares sentences with these, for which no sentence is quoted: Sézary syndrome (1 paper).